FASLG (Fas ligand)
Diseases named in the same sentence as FASLG in open-access papers (continued):
Sharing a sentence is not in itself a finding about the gene and the disease.
ZIKV infection (3 papers, 2021 to 2025). "We found that CD38, CD69, Fas Ligand, perforin, Ki67, and FcRγ expression was upregulated on NK cells during acute ZIKV infection, suggesting NK cells are activated, proliferating, and potentially cytotoxic during acute infection." (PMID 41000887, 2025). "When comparing healthy to post-acute ZIKV infection, CytoGLM identified FcRγ, Fas Ligand, and CD62L as predictive of post-acute infection when compared to healthy." (PMID 41000887, 2025). "We first evaluated markers predictive of acute ZIKV infection compared to healthy samples, which confirmed elevation of CD38, Fas Ligand, CD69, Ki67, and perforin as observed in our analysis of mean signal intensity." (PMID 41000887, 2025).
chronic hepatitis C (2 papers, 2015 to 2022). "In chronic hepatitis C patients, Fas and Fas ligand are elevated and Fas-induced apoptosis is one of the mechanisms for HCV-induced hepatocytes apoptosis." (PMID 26196694, 2015).
chronic kidney failure (2 papers, 2023 to 2025). "Recently, we showed that chronic kidney failure provokes an age-independently increased differentiation of CD8+ RTE Tresps via pathway 1, producing apoptosis-resistant CM Tresps which exhibited strong Fas ligand-mediated cytotoxicity." (PMID 37287988, 2023).
dilated cardiomyopathy (2 papers, 2019 to 2022). Cardiomyopathy which is characterized by dilation and contractile dysfunction of the left and right ventricles. "In a dilated cardiomyopathy mouse model overexpressing the Fas ligand (an inducer of apoptosis via caspase 3 activation), Fas ligand-activated periostin expression is mediated by the ERK1/2 pathway." (PMID 30884895, 2019). "CCN1 also increases levels of the myocardial apoptotic molecule Fas ligand (FasL), which activates the ERK1/2 pathway, leading to dilated cardiomyopathy and advanced heart failure." (PMID 36687680, 2022).
disc degeneration (2 papers, 2015 to 2023). "In NP cells, the overexpression of LINC00324 increases Fas ligand (FasL) expression and promotes disc degeneration." (PMID 37325630, 2023). "In human herniated lumbar IVD tissue, Fas ligand and Fas receptor analyzed by immunohistology, correlated significantly with patient age, but not with the degree of disc degeneration on magnetic resonance imaging." (PMID 25993467, 2015).
Fulminant hepatic failure (2 papers, 2012 to 2013). Hepatic failure refers to the inability of the liver to perform its normal synthetic and metabolic functions, which can result in coagulopathy and alteration in the mental status of a previously healthy individual. "TNF-alpha and Fas (CD95) binding Fas ligand (FasL) expression are activated in fulminant hepatic failure by CD8+-cells, NK-cells, and KCs and share common molecular pathways of instigation of apoptosis." (PMID 23091461, 2012).
Fulminant hepatitis (2 papers, 2009 to 2015). Acute hepatitis complicated by acute liver failure with hepatic encephalopathy occurring less than 8 weeks after the onset of jaundice. "Finally, the nanomicelle-based mRNA delivery was applied for treating fulminant hepatitis, which was induced by intraperitoneal injection of Fas-ligand." (PMID 26507781, 2015).
hearing loss (2 papers, 2024 to 2025). "The study highlights a significant inverse correlation between the expression levels of FASLG and miR-5195 and 3941, suggesting their potential involvement in the development of hearing loss." (PMID 40971385, 2025).
leprosy (2 papers, 2006 to 2023). Leprosy is a chronic infectious disease affecting primarily the skin and peripheral nervous system. "Expression of Fas ligand and apoptotic proteins is found in leprosy lesions and M. leprae has been shown to activate pro-apoptotic Bcl-2 genes, Bak and Bax." (PMID 16978419, 2006).
Multiple Organ Failure (2 papers, 2019 to 2022). A progressive condition usually characterized by combined failure of several organs such as the lungs, liver, kidney, along with some clotting mechanisms, usually postinjury or postoperative. "On the other hand, inappropriate overactivation of NKT cells can cause shock or multiple organ failure (MOF), including injury of the liver, lung, and kidney, via the TNF-α/Fas ligand (FasL) pathway." (PMID 35008905, 2022). "However, if NKT cells are inadequately activated, septic shock or multiple organ failure via TNF-α/Fas ligand (FasL) may occur." (PMID 31137499, 2019).
Myocardial fibrosis (2 papers, 2014 to 2021). "Activation of NF-κB can upregulate the expression of fibrosis-related factors, including transforming growth factor b1 (TGF-b1) and MMP-2, and increase Fas-ligand (Fas-L) expression to induce Fas-L–mediated apoptosis in the myocardium of diabetic rats, which leads to myocardial fibrosis." (PMID 33681206, 2021).
pheochromocytoma (2 papers, 2008 to 2013). "The ability of CRH to regulate cell apoptosis in several cells of different origin has been reported, and CRH has been shown to induce FASLG (Fas ligand) production and apoptosis in the rat pheochromocytoma cell line PC12 via activation of MAPK (p38 mitogen-activated protein kinase)." (PMID 23587111, 2013).
plague (2 papers, 2014 to 2020). Plague is a severe bacterial infection caused by the gram-negative bacterium Yersinia pestis. "We speculate that OMVs may allow for catalytically active Pla to act upon targets in the lungs during pneumonic plague, such as the newly discovered target Fas ligand, resulting in altered host cell apoptosis and innate immunity." (PMID 25198697, 2014).
retinoblastoma (2 papers, 2019 to 2023). A malignant tumor that originates in the nuclear layer of the retina. "FASLG, TNF, TNFRSF9, and TNFRSF1A, genes involved in FAS and TNF pathways, were expressed at significantly higher levels in Y79 retinoblastoma cells treated with magnetic hyperthermia compared to untreated cells." (PMID 31602343, 2019).
Salmonella Infections (2 papers, 2014 to 2017). Infections with bacteria of the genus SALMONELLA. "This analysis demonstrated that in the control-fed animals, Salmonella infection led to a transient downregulation of MAPK1, MAPK14, and FASLG at 1 dpi (p < 0.05)." (PMID 29181381, 2017).
sarcoidosis (2 papers, 2015 to 2021). Sarcoidosis is a multisystemic disorder of unknown cause characterized by the formation of immune granulomas in involved organs. "Increased susceptibility of circulating Treg cells towards CD95L (FAS ligand, FAS-L)-mediated apoptosis is present in sarcoidosis patients, leading to impaired survival of Treg cells." (PMID 34868074, 2021).
skin cutaneous melanoma (2 papers, 2022 to 2025). "FASLG has already been used in other signatures from necroptosis-associated genes to predict the prognosis of other cancers like renal clear cell carcinoma or skin melanoma." (PMID 39858052, 2025).
acute pancreatitis (1 paper, 2014). An acute inflammatory process that leads to necrosis of the pancreatic parenchyma. "This study investigated the relationship of Fas and Fas ligand (FasL) expression and apoptosis of lymphocytes in relation to the pathogenic immune response and infectious complications observed in experimental severe acute pancreatitis in mice." (PMID 24566874, 2014).
age-related hearing loss (1 paper, 2025). "Unlike previously reported miRNAs such as miR-21, these candidates had not been well-characterized in the context of FASLG regulation or age-related hearing loss." (PMID 40971385, 2025).
angiosarcoma (1 paper, 2025). A malignant tumor arising from the endothelial cells of the blood vessels. "The expression of Fas ligand (Fas-L), a potent inducer of apoptosis, was demonstrated in more than 70% of angiosarcomas, showing, as expected, an inverse correlation with tumor-infiltrating lymphocytes (TILs) and survival." (PMID 40004808, 2025).
brain injury (1 paper, 2023). Acute and chronic (see also brain INJURIES, CHRONIC) injuries to the brain, including the cerebral hemispheres, CEREBELLUM, and brain STEM. "Brain injury results in an increase in dsDNA in the blood, causing AIM2 inflammasome activation in blood monocytes and IL-1β release, which subsequently induces FAS ligand (FASL)-FAS-dependent T cell apoptosis leading to immunosuppression." (PMID 37216118, 2023).
chronic spontaneous urticaria (1 paper, 2019). "However, the role of the TNF-α system and Fas/Fas ligand (FasL) in the apoptosis-inducing pathways in chronic spontaneous urticaria (CSU), remain unclear." (PMID 30911316, 2019).
Conjunctiva (1 paper, 2025). "Conjunctiva-associated lymphoid tissue (CALT) and local immunoregulatory mediators (e.g., TGF-β2, Fas-ligand) may amplify the immune-modulatory effects of ultra-low doses." (PMID 40940942, 2025).
corneal infection (1 paper, 2013). A viral or bacterial infectious process affecting the cornea. "Dr. Hazlett’s group found that Fas ligand (FasL) knockout mice displayed more severe disease than wild-type mice after PA corneal infection, and demonstrated that treatment with substance P, an antiapoptotic neuropeptide, accelerates the disease progression of PA keratitis." (PMID 23878501, 2013).
diabetic nephropathy (1 paper, 2011). "In fact, attenuated expression of the apoptosis-mediated receptor Fas and the endogenous agonist Fas ligand (FasL) reduced tubular epithelial cell apoptosis in an in vivo model of diabetic nephropathy." (PMID 21251296, 2011).
endometrial adenocarcinoma (1 paper, 2022). "In contrast, mifepristone could inhibit cell growth and induce apoptosis in Ishikawa endometrial adenocarcinoma cells through caspase-3 activation and regulating apoptotic genes such as BCL2/BAX and FAS/FASLG." (PMID 35869506, 2022).
Evans syndrome (1 paper, 2018). "In addition, Fas and Fas ligand system defects (either decreased or increased activity) can be seen in CVID and Evans syndrome." (PMID 29849668, 2018).
factor deficiency (1 paper, 2023). "This process is a response to cell damage caused by endogenous and exogenous stress factors such as DNA damage, endoplasmic reticulum stress, irradiation, UV radiation, heat shock, growth factor deficiency, viruses, Fas ligand (FasL), cytokines from the TNF family, and others." (PMID 38002335, 2023).
Hypothermia (1 paper, 2021). Reduced body temperature due to failed thermoregulation. "Hypothermia seems to influence apoptotic and survival signaling pathways by affecting multiple molecules such as BCL-2 family members, protein kinase, cytochrome c, phosphatase and tensin homolog, Fas ligand, and apoptosis-inducing factor (AIF)." (PMID 34138955, 2021).
hypoxic-ischemic encephalopathy (1 paper, 2018). "This cohort study assessed whether Fas-ligand (FasL) and interleukin (IL)-6 levels in the cerebrospinal fluid (CSF) after hypoxic-ischemic encephalopathy (HIE) can serve as biomarkers of hypoxic brain injury in neonates." (PMID 30089504, 2018).
insulinoma (1 paper, 2025). "Isolated mouse islets and insulinoma cell lines were analyzed to assess the expression of Fas, Fas ligand, and Fas-associated death domain (FADD) using techniques such as reverse transcription-polymerase chain reaction (RT-PCR), WB, and immunofluorescence." (PMID 39859479, 2025).
ischemia reperfusion injury (1 paper, 2015). Adverse functional, metabolic, or structural changes in ischemic tissues resulting from the restoration of blood flow to the tissue (reperfusion), including swelling; hemorrhage; necrosis; and damage from free radicals. "Our results demonstrated that OGDR insult enhanced the expression of Fas-L and Bax, as well as cleavage of caspases 3 and p115, suggesting that apoptosis via the Fas/Fas ligand signalling system plays an important role in the development of ischemia-reperfusion injury." (PMID 26199678, 2015).
ischemic disease (1 paper, 2020). Lack of blood supply to an area of the body, resulting in impairment of tissue oxygenation. "On the contrary, transgenic mice with miR-21 overexpression demonstrated a reduction in the infarct area and CF fibrosis as well as the downregulation of phosphatase and tensin homolog (PTEN) protein and Fas ligand (FasL) in ischemic diseases." (PMID 33329700, 2020).
Listeria monocytogenes infection (1 paper, 2013). "While a similar increase or decrease of CD8 T cell response is observed against Listeria monocytogenes infection in wild-type (WT) and Fas ligand (FasL) mutant mice, FasL mutant mice had mainly TEM population in the long term when compared to WT mice that carried majorly TCM population." (PMID 24171157, 2013).
liver cirrhosis (1 paper, 2022). "The prognostic value of a marker combination with soluble Fas-ligand and GGT in patients with liver cirrhosis should be further evaluated." (PMID 35176084, 2022).
liver dysfunction (1 paper, 2025). "Accumulated CD8+ T cells in the liver can trigger hepatocyte apoptosis by expressing Fas ligand (FasL), which binds to Fas receptors on hepatocyte surfaces, thereby exacerbating liver dysfunction." (PMID 41462924, 2025).
nephrotic syndrome (1 paper, 2021). A collection of symptoms that include severe edema, proteinuria, and hypoalbuminemia; it is indicative of renal dysfunction. "Moreover, apoptosis markers including caspase-3 and Fas-Ligand did not stain significantly in the podocytes of these mice, indicating that podocyte detachment may not have a major role in the PAN-induced nephrotic syndrome model." (PMID 34948207, 2021).
Osteopenia (1 paper, 2021). Osteopenia is a term to define bone density that is not normal but also not as low as osteoporosis. "Liu et al71 showed that systemic injection of SHEDs via the tail vein ameliorated OVX‐induced osteopenia by activating the Fas ligand (FasL)‐mediated Fas pathway, leading to up‐regulation of Tregs and down‐regulation of Th1 and Th17 cells." (PMID 33210341, 2021).
pestivirus infection (1 paper, 2013). "FASLG, an IFN-stimulated gene, has also been associated with cell death/apoptosis of uninfected bystander cells, and attack/killing of infected cells in pigs that recovered from a pestivirus infection." (PMID 24341289, 2013).
pterygium (1 paper, 2024). A wedge-shaped fibrovascular lesion arising from the bulbar conjunctiva and extending to the cornea. "For instance, CASP1 could participate in pyroptosis through activated IL1B and IL18, and FASLG could be involved in pterygium fibroblasts, suggesting that they might play a role in pterygium pathogenesis." (PMID 38732006, 2024).
spondylolisthesis (1 paper, 2015). A condition in which there is forward displacement of a vertebral bone over the on below it. "Fas ligand was shown on human IVDs, but appears to display a negative correlation with IVD degeneration in spondylolisthesis." (PMID 25993467, 2015).
spongiotic dermatitis (1 paper, 2022). A generic term for a broadly defined histopathologic pattern characterised by “eczema”, often associated with an increase in eosinophils occurring in a background of contact dermatitis, atopy and drug reactions. "Studies in this field have revealed the importance of IgE-mediated delayed-type hypersensitivity, the Fas/Fas-ligand system, and cell-mediated cytotoxicity in inducing the apoptosis of keratinocytes in spongiotic dermatitis." (PMID 35743125, 2022).
tumor (1,667 papers, 2000 to 2026). "The inflammatory response at the margin of metastases induces Fas expression in adjacent hepatocytes, making them susceptible to damage by Fas‐ligand‐bearing lymphocytes or tumor cells, thereby promoting tumor invasion." (PMID 40027151, 2025). "Alternatively, tumor cells expressing the Fas molecule become susceptible to death when interacting with CD8+ T cells expressing the Fas ligand (FasL), also resulting in apoptosis." (PMID 40430079, 2025). "Tumor-associated endothelial cells (TECs) in CRC express immune-modulatory molecules like Fas ligand (FasL) and E-selectin, promoting the exclusion of cytotoxic T cells while facilitating neutrophil recruitment." (PMID 41244711, 2025). "This alteration was accompanied by an upregulation of the tumor-associated FASLG signaling pathway and a concomitant downregulation of the tumor-promoting SPP1 pathway." (PMID 40725216, 2025). "Thirdly, Fas ligand (Fas-L) on the tumour endothelial barrier causes the elimination of CD8+ T cells rather than regulatory T cells because of the high c-FLIP expression on regulatory T cells." (PMID 40647497, 2025). "We observed that tumours with CASP8 mutations had higher mean FASLG expression, suggesting that the OSCC lines were resistant to FasL‐mediated apoptosis." (PMID 37443405, 2023). "Other studies have shown a similar correlation between CASP8 mutations and FASLG expression in HNSCC tumours with a high level of immune infiltration." (PMID 37443405, 2023). "Our study revealed several key genes with high degrees involved in the subnetwork, including CD274, CD20, and FASLG that have been widely used in clinical tumor treatment, and they were positively associated with poor prognosis in CRC." (PMID 36660243, 2023). "Specifically, tumor-associated endothelial cells can produce molecular factors such as PD-L1, Fas ligand (FasL), or vascular endothelial growth factor (VEGF) that critically modulate immune responses in the tumor environment." (PMID 36978029, 2023). "Co‐expression analysis of the TCGA HNSCC clinical dataset for FASLG expression in CASP8 mutated samples supports our proposal that tumour cells are protected from FasL‐mediated apoptosis." (PMID 37443405, 2023). "The association of Fas’ cysteine-rich signal peptide with the Fas ligand (FasL) is a critical regulator of tumor growth." (PMID 36386956, 2022). "As a result of CNV analysis in pan-cancer targeting of these necroptosis risk model genes, FLT3, CD40, and FASLG genes have high CNVs in various tumor types." (PMID 36675706, 2022). "The Factor associated suicide (Fas) and Fas ligand (FasL) pair function as a guardian against autoimmunity and tumor genesis." (PMID 33981213, 2021). "Fas is a classical death receptor involved in the Fas/Fas ligand (FasL) apoptosis pathway, which has anti-tumor activity, and can cause cascade reactions that lead to cell death." (PMID 33718153, 2021). "Cancer cell lysis by CAR T-cells is classified into three killing mechanisms: Fas/Fas ligand (FasL) pathway-associated tumor cell lysis, a cytokine-induced killing mechanism, and tumor cell lysis by granzyme and perforin." (PMID 31658644, 2019). "Tumor derived exosomes express the T-cell apoptosis-inducing molecule Fas Ligand (FasL) in vivo and in vitro causing apoptosis of cytotoxic CD8+ T-lymphocytes." (PMID 30925921, 2019). "Fas ligand (FasL) causes apoptosis in Fas-expressing cells and serves as a major death-inducing factor in the immune response against tumor cells." (PMID 24919191, 2014). "Expression of high levels of Fas Ligand, perforin, and granzyme B by iNKT cells underlies their cytolytic activity against CD1d+ tumor cells and myeloid cells with immunosuppressive function present in the tumor microenvironment." (PMID 25349699, 2014). "Recently, it was found that downregulation of the EP1 receptor leads to reduced Fas ligand expression which is associated with tumor growth and decreased tumor-induced immune suppression." (PMID 23975167, 2013).